SCAP (SREBF chaperone)
Diseases named in the same sentence as SCAP in open-access papers (continued):
Sharing a sentence is not in itself a finding about the gene and the disease.
tumor (continued). "SCAP has been increasingly recognized as a central regulator in the tumor cells lipogenesis." (PMID 31083642, 2019). "Inhibition of the SCAP–SREBP pathway leads to impaired tumor growth." (PMID 31083642, 2019). "Trapped RA16 was 100-fold higher than trapped SCAP at the tumor site, indicating that the entrapment of syn-RA16 in tumor tissues may be attributed to its specific binding in vivo." (PMID 31827170, 2019). "Furthermore, silencing SCAP significantly inhibited tumor spheroid formation and decreased expression of genes associated with cancer stem cells." (PMID 29449559, 2018). "SCAP modification and inhibition inhibit tumor growth through SREPBs50,56–58." (PMID 29950559, 2018). "Single cell RNA sequencing indicated that loss of SCAP suppressed SREBP-dependent transcriptional programs in endocrine and exocrine precursors, but was associated with enhanced SREBP2 activity in fibroblastic populations, compatible with formation of a pro-tumorigenic tumor microenvironment." (PMID 41986652, 2026). "Moreover, animal xenograft models showed that the combination of the specific SCAP inhibitor lycorine and sorafenib was sufficient to inhibit tumour growth, suggesting that targeting SCAP may be a new therapeutic strategy for sorafenib-resistant HCC." (PMID 35354475, 2022). "In addition, it has also been reported that a reduction in the levels of sterols in tumor cells will cause SREBP1 to be synthesized into precursors within the endoplasmic reticulum (ER), thus creating protein complexes with SREBP-cleavage-activating protein (SCAP)." (PMID 34039951, 2021). "Several small molecules have been shown to target the SCAP and SREBP interaction to disrupt SREBP1 activation and reduce tumor growth in a variety of conditions." (PMID 40427160, 2025). "Using the diarylthiazole derivative fatostatin A, which binds to SCAP and blocks the translocation of the SCAP/SREBP complex to the Golgi, we were able to significantly curtail the survival of PDT-treated mouse SCCVII tumor cells." (PMID 39675508, 2025). "We demonstrate that the SREBP pathway and SCAP are required for PDAC cell survival and tumor growth, making the SREBP pathway a candidate therapeutic target for PDAC." (PMID 39240063, 2024). "Collectively, these results demonstrate that SCAP and SREBP pathway activity are required for PDAC cell and tumor growth, identifying SCAP as a potential therapeutic target for PDAC." (PMID 39240063, 2024). "It has been suggested that the SCAP/SREBP signalling pathway has a synergistic inhibitory effect with anti-PD-1 therapy in M2-TAM and Treg cells and enhances anti-tumour immunity." (PMID 38245525, 2024). "Cholesterol accumulation enhances SCAP and INSIG binding and leads to reduced adipogenesis and tumor suppression." (PMID 36969840, 2023). "The binding of ammonia to SCAP induces sequential conformational changes, leading to the activation of SCAP–Insig dissociation, ultimately resulting in the translocation of SCAP–SREBP, SREBP activation, and lipogenesis, thereby promoting tumor growth." (PMID 40052303, 2025). "Similarly, botulin, employing the same mechanism of disrupting SCAP–SREBP interaction, reduces tumor growth in models of prostate, breast, lung, and hepatic cancers." (PMID 40427160, 2025). "Finally, we measured the protein expression of SCAP, AMPK, p-AMPK, P62, and cleaved LC3-II in the tumour tissues by using Western blots and IF staining." (PMID 35354475, 2022). "SCAP knockdown by siRNA also partially blocked RA-XII-induced cell death in HepG2 cells, demonstrating that RA-XII-mediated SREBP suppression and anti-tumor effects are SCAP-dependent." (PMID 31083642, 2019). "NCI-H460 tumor-bearing mice were injected with syn-RA16, trans-RA16, or SCAP." (PMID 31827170, 2019). "Moreover, RA-XII downregulated the expression of SREBP cleavage-activating protein (SCAP), an upstream regulator of SREBP, and siRNA of SCAP prevented its restrained effects on tumor growth and lipogenesis." (PMID 31083642, 2019).
tumor (continued). "Moreover, the exposure to SCAP and SREBP siRNAs could block the anti-tumor and anti-lipogenesis effects of RA-XII in HepG2 cells, suggesting that anti-tumor and anti-lipogenesis effects of RA-XII may be mediated through down-regulation of the SCAP–SREBP pathway." (PMID 31083642, 2019).
cancer (20 papers, 2010 to 2025). A tumor composed of atypical neoplastic, often pleomorphic cells that invade other tissues. "Thus, the increase in SREBP associated with the reduction in SCAP may contribute to an increase in the synthesis of fatty acids, triglycerides, and cholesterol, essential for the development of cancer." (PMID 37469457, 2023). "Fatostatin, Betulin, and Xanthohumol have been shown to suppress cancer progression not only via the SCAP-SREBP pathway but also through inhibition of mTOR, MAPK, and Notch signaling." (PMID 40308757, 2025). "When the stability of INSIG/SCAP in cancer cells is affected, it also affects the “ship” heading to the Golgi for the next step of cutting activation." (PMID 36969840, 2023). "Therapeutic strategies against cancer based on lowering cellular cholesterol content are in clinical evaluation, and SCAP/SREBPs were suggested as promising metabolic targets for cancer therapy." (PMID 34681843, 2021). "It has been reported that elevated expression of SCAP–SREBP pathway has been detected in several cancer types and was closely correlated with malignant transformation, cancer progression, and metastasis." (PMID 31083642, 2019). "Recent studies identified UT-59 as a SCAP-specific inhibitor that could open the door to developing therapeutic leads for cancer; however, its therapeutic efficacy and mechanistic details require further experimental validation." (PMID 40308757, 2025). "To examine the requirement of the SREBP pathway for cancer cell growth on a wider scale, we examined the Chronos dependency scores for SCAP, SREBF1, and SREBF2 using the Cancer Dependency Map database, which contains genome-wide CRISPR loss-of-function screen data for hundreds of cancer cell lines." (PMID 39240063, 2024). "The classical inhibitors targeting SCAP/SREBPs in cancer cells." (PMID 33014877, 2020). "The EGFR signaling pathway enhances SCAP N-glycosylation to deactivate SREBP-1 by promoting glucose uptake, and SREBP-1 can promote the progressive metastasis of cancer." (PMID 38319706, 2024). "An RNA-binding protein, Lin28 enhances SREBP-1 translation and maturation to promote cancer progression by directly binding to the mRNAs of both SREBP-1 and SCAP." (PMID 35912181, 2022). "In line with the previous report, this finding highlights aberrant activation of SREBP-1/SCAP axis to amplify cancer stem cells that are lacking differentiation and depend on lipogenesis, as this axis is also the master regulator of lipid metabolism." (PMID 35806291, 2022). "A total of 43 genes reside within 10 kb of these regions (column B), including those involved in cancer pathways (e.g. MMP2), angiogenesis (e.g. VEGFA), hypoxia response (e.g. SCAP), and neural development (e.g. KCNQ2), with downregulation of these loci being the dominant transcriptional effect." (PMID 29587824, 2018).
infection (8 papers, 2014 to 2024). The state of being infected such as from the introduction of a foreign agent such as serum, vaccine, antigenic substance or organism. "25-Hydroxycholesterol (25HC), a cholesterol metabolite inhibiting infection by a broad range of pathogenic viruses, works indirectly through a 25HC sensor protein to elicit SCAP-Insig binding." (PMID 30631056, 2019). "In the presence of insulin in the culture medium, Klf2 increased the protein level of SCAP in primary hepatocytes after 48 h after Ad-ALB-Klf2 infection." (PMID 37949368, 2024). "Increase of WBC count together with lymphocyte decrease in patients with CAP compared to healthy controls, especially those with sCAP, indicates the natural response to severe infection, which is consistent with previous studies." (PMID 35610602, 2022). "The level of SREBP-1c cleavage, the staining intensity of SREBP2 and SCAP in the liver of siGP73 mice were all significantly reduced compared to that of the wild-type mice at day 1 post infection." (PMID 29097707, 2017). "Analysis of a large library of insertionally mutagenized human haploid cells and a siRNA genomic screen converged on components (SREBP-2, SCAP, S1P and S2P) of the sterol regulatory pathway as critically important for infection by ANDV." (PMID 24516383, 2014). "To explore the importance of the cholesterol regulatory complex for ANDV glycoprotein-dependent infection in human cells we developed a Transcription Activator Like Exonuclease (TALEN) pair that disrupted the coding region of SCAP (TALENSCAP)." (PMID 24516383, 2014). "SCAP disruption was quantified pre- and post-infection using a quantitative PCR heteroduplex cleavage assay." (PMID 24516383, 2014). "The results obtained from the siRNA and haploid cell screens indicated that components of the sterol regulatory pathway (SREBF2, SCAP, S1P, and S2P) were required for rVSV-ANDV infection." (PMID 24516383, 2014). "After infection with rVSV-ANDV, the SCAP-disrupted population increased to ∼43%." (PMID 24516383, 2014). "Among these, disruption of the canonical SREBP regulators SCAP, MBTPS1, and MBTPS2 conferred resistance to SARS-CoV-2 infection, with a similar effect for infection with the ACE2-independent HCoV-OC43 and HCoV-229E but not the ACE2-dependent HCoV2-NL63." (PMID 35231079, 2022). "Infection with VSV-(HTNV) decreased by roughly 1-log in cells null for S1P and SCAP, but not S2P, suggesting a more modest dependence on this pathway." (PMID 24516383, 2014).
metabolic disease (7 papers, 2016 to 2025). A congenital disorder (due to inherited enzyme abnormality) or acquired (due to failure of a metabolically important organ) disorder resulting from an abnormal metabolic process. "To date, several drugs have been developed to inhibit lipid synthesis by targeting SCAP/SREBP activities in various metabolic disorders." (PMID 38256181, 2024). "SCAP, a cholesterol sensor involved in lipid imbalances, regulates metabolic diseases, but its role in astrocytes remains unclear." (PMID 41016959, 2025). "Therefore, SCAP presents a promising target for pharmacologic suppression in the treatment of metabolic diseases." (PMID 32385422, 2020). "Because SCAP plays a pivotal role in the regulation of cholesterol homeostasis, targeting it continuously could be an attractive strategy for the treatment of metabolic diseases." (PMID 35354475, 2022). "SCAP is a cholesterol sensor that regulates signal transduction for intracellular cholesterol homeostasis, and its dysregulation may affect the development of metabolic disorders, suggesting that cholesterol metabolism plays an important role in lean NAFLD pathogenesis." (PMID 39000518, 2024). "SCAP, a cholesterol sensor, impacts MASLD and other metabolic diseases." (PMID 38256181, 2024).
kidney disease (1 paper, 2023). "Protein levels of SCAP, FASN, PLIN2, NLRP3, and GSDMD were higher in fibrotic human kidney tissue samples, likely indicating that DNL could be associated with kidney disease." (PMID 38051585, 2023). "Healthy controls and kidney disease samples showed strong expression of DNL genes, including ACSS2, NR1H3 (liver X receptor α [LXRA]), NR1H4 (farnesoid X receptor [FXR]), SREBF1, SCAP, PLIN2, PLIN5, ACACAB, ATP citrate lyase (ACLY), and FASN in PT cells and some other tubule cells." (PMID 38051585, 2023). "Deletion of SCAP or FASN in tubule cells or pharmacological inhibition of FASN protected cultured tubular cells from profibrotic gene expression and mice from tissue fibrosis, highlighting the importance of DNL in kidney disease development." (PMID 38051585, 2023).
SCAP also shares sentences with these, for which no sentence is quoted: Insulin resistance (4 papers); fibrosis (3); acute myocardial infarction (2); hypertriglyceridemia (2); non-alcoholic fatty liver disease (2); pancreatic cancer (2); adenocarcinoma (1); amyotrophic lateral sclerosis (1); arteriosclerosis (1); bladder cancer (1); cardiovascular disease (1); chronic kidney disease (1); Cirrhosis (1); Cognitive impairment (1); colon adenocarcinoma (1); connective tissue disease (1); coronary atherosclerosis (1); Diabetic Nephropathy (1); esophageal cancer (1); ganglioneuroblastoma (1); Gliosis (1); glomerulosclerosis (1); hematological malignancy (1); hepatic diseases (1); inflammation (1); melanoma (1); neuroblastic tumor (1); neuroendocrine tumors (1); Niemann-Pick disease (1); non-small cell lung carcinoma (1).
A further 7 diseases each share a sentence with SCAP in 1 paper.